KEAP1 (kelch like ECH associated protein 1)
Diseases named in the same sentence as KEAP1 in open-access papers (continued):
Sharing a sentence is not in itself a finding about the gene and the disease.
diabetic retinopathy (14 papers, 2017 to 2025). "Our findings indicate the role of oxidative stress along with overweight, through increased TOS level, and also Keap1 polymorphism in diabetic retinopathy pathogenesis as the minor A allele of Keap1 is associated with lower Keap1 expression." (PMID 34861061, 2022). "Our study indicated the Keap1 A allele increased the risk of diabetic retinopathy by 2.36‐fold." (PMID 34861061, 2022). "We explored differences in the DNA methylation statuses of PSMA6, PSMB5, HIF1A, and KEAP1 gene promoter regions in patients with type 1 diabetes and different diabetic retinopathy (DR) stages." (PMID 38927561, 2024). "Epigenetic modification at the promoters of Keap1 and Nrf2 modulates oxidative stress during the progression and development of diabetic retinopathy." (PMID 35340204, 2022). "The Keap1‐Nrf2 pathway in the streptozotocin‐induced diabetic model had a protection role against the onset and/or diabetic retinopathy progression." (PMID 34861061, 2022). "In addition, a recent study showed that fenofibrate attenuates oxidative stress in diabetic retinopathy through Keap1/Nrf2, suggesting that cardiomyocytes stimulated by fenofibrate were protected from oxidative stress following a pathway that includes Nrf2." (PMID 33505452, 2021). "Considering that antioxidant signal transduction is a promising therapeutic target in retinopathy diseases, targeting TGF-β1 to promote Nrf2/Keap1/ALDH3A1/HO-1 signaling may be a candidate therapeutic approach for diabetic retinopathy." (PMID 32899874, 2020). "Besides its validated activity as tyrosine kinase receptor inhibitor, we found in our in vitro models of diabetic retinopathy that axitinib exerts antioxidant, anti-inflammatory and anti-angiogenic effects, also regulating Nrf2 expression, likely through covalent binding to Keap1-BTB domain." (PMID 38953109, 2024). "In diabetic retinopathy research, SETD7 promotes KEAP1 expression by enhancing H3K4me1 at the KEAP1 promoter region, accelerating retinal endothelial cell damage." (PMID 41203594, 2025). "This review focuses on the effects of oxidative stress and the role of a particular antioxidant system—the Keap1-Nrf2-ARE pathway—on ocular diseases, specifically age-related macular degeneration, cataracts, diabetic retinopathy, and glaucoma." (PMID 28473877, 2017). "In addition to H3K4me2 in the Nrf2 promoter, the methylation of H3K4 by both Set7/9 and stimulated protein-1 (SP1) is enriched in the Keap1 promoter, which promotes the biosynthesis of GSH and regulates oxidative stress in diabetic retinopathy." (PMID 35340204, 2022). "According to Radhakrishnan R and Kowluru RA, the lncRNA MALAT1 can adjust the antioxidant defense in diabetic retinopathy through the Keap1/Nrf2 pathway, and inhibiting the lncRNA MALAT1 may help to protect the retina from oxidative damage and prevent or slow diabetic retinopathy." (PMID 38907191, 2024). "Keap1 prevents Nrf2 translocation from the cytosol to the nucleus to bind with ARE4, thereby downregulating the transcription of GCLC and largely attenuating the biosynthesis of GSH, indicating that the Nrf2-Keap1-GCLC pathway plays an important role in diabetic retinopathy." (PMID 35340204, 2022). "Interestingly, in diabetic retinopathy development, SETD7 knockout inhibited Keap1 expression by preventing lysine 4 methylation on histone H3 (H3K4), stimulating protein-1 (Sp1) binding to the Keap1 promoter, and promoting Nrf2 expression." (PMID 36185600, 2022).
pulmonary fibrosis (14 papers, 2014 to 2025). Chronic progressive interstitial lung disorder characterized by the replacement of the lung tissue by connective tissue, leading to progressive dyspnea, respiratory failure, or right heart failure. "Meanwhile, studies have shown that Keap1-Nrf2 is associated with pulmonary fibrosis, and the protective effect of p65 in pulmonary fibrosis can be reversed by Nrf2 knockout." (PMID 35898772, 2022). "and lung fibrosis by regulating Keap1/p65/Nrf2 signal pathway, and uncovering the underlying mechanisms might shed light on the discovery of therapeutic agents for PQ intoxication." (PMID 30734183, 2019). "Furthermore, curcumin and nanocurcumin inhibited ROS production and alleviated paraquat (PQ) -induced pulmonary fibrosis by modulating gene expression of the kelch-like ECH-associated protein 1 (KEAP1), HO-1, NQO1, and glutathione-S-transferase (GST) in lung tissue." (PMID 41357857, 2025). "Another study suggested that Sohlh2 can promote pulmonary fibrosis by transcriptional repression of the p62/Keap1/Nrf2 mediated anti-oxidative signaling pathway." (PMID 40170095, 2025). "Through proteomics, the potential protein-binding sites of lung fibrosis induced by ferroptosis induced by PQ inhibition of the Keap1/Nrf2 signaling pathway were investigated." (PMID 37812357, 2023). "Our study demonstrated that Sohlh2 overexpression inhibited the activation of the p62/Keap1/Nrf2 signaling pathway by repressing p62 transcription to induce oxidative stress in AECIIs, which led to severe pulmonary fibrosis." (PMID 37875506, 2023). "The results show that the phycocyanobilin peptide was able to alleviate oxidative and inflammatory damage in cells through the Keap1-Nrf2-HO-1 pathway, which in turn relieved pulmonary fibrosis symptoms." (PMID 36355019, 2022). "In a word, autophagy relieves pulmonary fibrosis through the activation of the Keap1/Nrf2 signaling pathway." (PMID 35898772, 2022). "In this paper, we have explored the mechanism of autophagy in pulmonary fibrosis and to clarify the mechanism of the interaction between Keap1/Nrf2 signaling pathway and autophagy in pulmonary fibrosis." (PMID 35898772, 2022). "It has been indicated that bleomycin-induced pulmonary fibrosis showed suppression of Keap1-Nrf2 in vivo." (PMID 34445113, 2021). "In conclusion, we found that high dose of PQ inhibits cell viability and autophagy and promotes cell death as well as mice lung fibrosis by regulating Keap1/p65/Nrf2 signal pathway." (PMID 30734183, 2019). "The in vivo experiments also verified that PQ induces mice lung fibrosis, inhibits cell proliferation, and promotes cell death and inflammatory cytokine secretion by regulating Keap1/p65/Nrf2 signal pathway." (PMID 30734183, 2019). "In vivo experiments also showed that high-dose PQ promotes inflammatory cytokines secretion, lung fibrosis and cell apoptosis, inhibits cell proliferation in mice models by regulating Keap1/p65/Nrf2 signal pathway." (PMID 30734183, 2019). "Finally, transcriptomics and proteomics were combined to explore the molecular mechanism of PQ poisoning regulating the Keap1/Nrf2 signaling pathway inducing ferroptosis leading to pulmonary fibrosis." (PMID 37812357, 2023). "Our results suggest that PQ can regulate Keap1/Nrf2 signaling pathway, leading to increased lipid peroxidation and abnormal iron uptake, thereby inducing iron death and exacerbating the progression of pulmonary fibrosis." (PMID 37812357, 2023). "To further confirm the mechanism of Sohlh2 in the regulation of AECII oxidative stress during the development of pulmonary fibrosis, we examined the effect of Sohlh2 on regulating the p62/Keap1/Nrf2 signaling pathway in the lung tissues of 8 M and HFD-fed mice." (PMID 37875506, 2023). "Autophagy alleviating pulmonary fibrosis through activation of Keap1/Nrf2 signaling pathway." (PMID 35898772, 2022).
pulmonary fibrosis (continued). "In this study, we have found that the expression of Keap1 and Nrf2 are abnormal in mouse models of pulmonary fibrosis and pulmonary fibrosis cells, that is, Keap1 is highly expressed and Nrf2 is low, indicating that the Keap1/Nrf2 signaling pathway is affected by lung fibrosis." (PMID 35898772, 2022). "Therefore, we concluded that high-dose PQ (500 μM) inhibits 16HBE cell proliferation and autophagy, promotes cell death and mice lung fibrosis by regulating Keap1/p65/Nrf2 signal pathway." (PMID 30734183, 2019). "In addition, administration of EGCG in a rat model of bleomycin-induced pulmonary fibrosis has demonstrated the involvement of nuclear factor erythroid-derived 2-related factor 2 (Nrf2) and Kelch-like ECH-associated protein 1 (Keap1) signaling." (PMID 27452398, 2016). "Until now, several studies have identified changes in Keap1-Nrf2 signaling in models of respiratory diseases, such as acute respiratory distress syndrome (ARDS)/acute lung injury (ALI), chronic obstructive pulmonary disease (COPD), idiopathic pulmonary fibrosis (IPF), and asthma." (PMID 34445113, 2021). "However, the regulation of Keap1/Nrf2 signaling pathway by PQ poisoning and the molecular mechanism of whether Keap1/Nrf2 signaling pathway induces Ferroptosis and leads to pulmonary fibrosis is still lacking." (PMID 37812357, 2023).
squamous cell carcinoma (14 papers, 2013 to 2025). A carcinoma arising from squamous epithelial cells. "KEAP1 is mutated in approximately 20% of lung adenocarcinomas and squamous cell carcinomas, as identified by cancer genome sequencing studies." (PMID 41378285, 2025). "However, a trend was observed that low KEAP1 expression is associated with poor survival in squamous carcinoma patients, and squamous carcinoma patients are the subgroups that will use chemotherapy in the clinic." (PMID 31659154, 2019). "The prevalence of mutations in either KEAP1 or NFE2L2 (the gene encoding NRF2) is approximately 30% overall in NSCLC, with KEAP1 mutations occurring primarily in adenocarcinoma and NFE2L2 in squamous cell carcinoma." (PMID 33920029, 2021). "Although, LCNECs also harbored alterations commonly observed in adenocarcinomas and squamous cell carcinomas, even LCNECs with such alterations in KEAP1 or STK11 were primarily found in transcriptional subclasses shared with SCLC." (PMID 29535388, 2018). "In the present study, Keap1 mutations were only identified in patients with adenocarcinoma, but not squamous cell carcinomas." (PMID 24137397, 2013). "The EDF genes specific for the histology subtype also include TSHR, KEAP1, and EGFR in adenocarcinoma, and NOTCH1, PIK3CA in squamous cell carcinoma." (PMID 33078899, 2020).
type 2 diabetes (14 papers, 2012 to 2026). "As demonstrated in an earlier type 2 diabetic wound model (Bitar & Al‐Mulla, 2011), the current results indicated that HFD/STZ‐induced type 2 diabetes leads to irregular Nrf2/Keap1 and Nrf2/HO‐1 signaling by unbalancing GSK‐3β/Fyn/Nrf2 signaling in the liver." (PMID 37823118, 2023). "Recently, bardoxolone methyl, which activates the Keap1-Nrf2 anti-oxidant pathway, was shown to protect kidney function in patients with type 2 diabetes." (PMID 22813067, 2012). "Our study revealed a significant relative increase in liver GSK‐3β (p < .0001), Fyn (p < .01), and Keap‐1 (p < .0001) levels by 53%, 53%, and 38%, respectively, in response to the induction of type 2 diabetes compared to the levels observed in healthy control rats." (PMID 37823118, 2023). "In type 2 diabetes, improving the nuclear factor erythroid 2–related factor 2 (Nrf2)/kelch like ECH‐associated protein 1 (Keap1)/antioxidant response element signaling pathway mediates antioxidant defense, inhibits inflammation, and promotes cell survival; thus, it may attenuate oxidative damage." (PMID 37823118, 2023).
acute kidney injury (13 papers, 2021 to 2026). Sudden and sustained deterioration of the kidney function characterized by decreased glomerular filtration rate, increased serum creatinine or oliguria. "The Keap1/Nrf2/HO-1 signaling pathway can inhibit ferroptosis and alleviate cisplatin-induced acute kidney injury." (PMID 39306640, 2025). "In an LPS-induced acute kidney injury model, KEAP1-mediated NRF2/antioxidant response element system activation was critical in alleviating oxidative stress and ferroptosis." (PMID 37891461, 2023). "This study investigated the efficacy of geraniol to prevent methotrexate-induced acute kidney injury and via scrutinizing the Keap1/Nrf2/HO-1, P38MAPK/NF-κB and Bax/Bcl2/caspase-3 and -9 pathways." (PMID 34889889, 2021). "As for the renal actions, geraniol exhibited protection against cyclosporine A-induced nephrotoxicity via lowering inflammation mediators, including (ICAM-1, IL-18, and NF-κB), protection against methotrexate-induced acute kidney injury via Keap1/Nrf2/HO-1 and MAPK/NF-κB pathways." (PMID 36009287, 2022). "A recent study documented that PX could suppress aristolochic acid-induced renal failure by suppressing oxidative stress through the activation of Keap1-Nrf2/HO-1 signaling pathway." (PMID 33653364, 2021). "When PEG-CNPs treat acute kidney injury, in the renal cortex, PEG-CNPs exhibit great ROS scavenging activity to break down H2O2 and subsequently regulate genes related to ROS by activating the Nrf2/Keap1 signaling pathway." (PMID 37507801, 2023).
colon carcinoma (13 papers, 2011 to 2023). "In our study, high levels of AKRs expression in KEAP1 knockdown colon cancer cells appear to be associated with the resistance to 4HNE toxicity and diminished protein adducts formation." (PMID 23766854, 2013). "The appropriate basal function of Nrf2 and Keap1 is essential for oncogenic process prevention in the colon; however, Nrf2 overactivation, resulting from Nrf2-induced inflammation and resistance to chemotherapy, increases colon cancer risk." (PMID 36539411, 2022). "For example, oxaliplatin activates the Keap1/Nrf2 pathway and confers protection against the cytotoxicity of anticancer drugs in colon cancer cells." (PMID 29899863, 2018). "These indicate that KEAP1-knockdown is an effective genetic tool to activate NRF2 signaling in colon cancer cells, and AKRs are a highly inducible gene group regulated by NRF2 in human cells." (PMID 23766854, 2013). "Our results show that KEAP1-knockdown colon cancer cells exhibit significantly enhanced AKRs expression and elevated cell viability in response to H2O2 or menadione treatments." (PMID 23766854, 2013). "For this, we established stable colon cancer cell lines with KEAP1 knockdown as a model of pure genetic activation of NRF2 and monitored expression levels of thirty NRF2 target genes, which were known from studies with the murine system." (PMID 23766854, 2013). "Further, we explored the possible involvement of AKRs in hydrogen peroxide and 4HNE toxicities by examining the 4HNE adduct formation and cytotoxicity in KEAP1 silenced colon cancer cells." (PMID 23766854, 2013). "It has been reported that Nrf2 can be activated by 5FU, possibly as a result of drug-induced ROS production, in the Keap1-expressing human colon cancer HT-29 cell line." (PMID 21489257, 2011). "The Keap1-Nrf2 signaling pathway is the most important anti-oxidative stress pathway in vivo, and its aberrant activation has been found in various tumors, such as esophageal cancer and colon cancer." (PMID 34466284, 2021). "In order to confirm the effect of KEAP1-knockdown on NRF2 target genes expression and oxidative stress susceptibility, another type of colon cancer cell line HCT116, which has a distinct genetic mutation profile, was used for the establishment of stable KEAP1 knockdown cell line (shKEAP1 HCT116)." (PMID 23766854, 2013). "(A, D, G, J) Keap1, DDB2, WSB2, or Rbx1 siRNAs were transiently transfected into human colon cancer cell line HCT-116 cells." (PMID 37943017, 2023). "In the current study, we have investigated the effect of KEAP1-knockdown on NRF2 target gene expression and its toxicological implication using human colon cancer cells." (PMID 23766854, 2013). "In the present study, we aimed to investigate the effect of KEAP1 knockdown on NRF2 target gene expression and its toxicological implication using human colon cancer cells." (PMID 23766854, 2013).
head and neck squamous cell carcinoma (13 papers, 2015 to 2025). A squamous cell carcinoma that arises from any of the following anatomic sites: lip and oral cavity, nasal cavity, paranasal sinuses, pharynx, larynx, and salivary glands. "Chemoresistance mediated by KEAP1 mutations has also been observed in prostate cancer, melanoma, and head and neck squamous cell carcinoma (HNSCC), indicating poor treatment response." (PMID 39061847, 2024). "In head and neck squamous cell carcinoma (HNSCC), abnormal activation of the NRF2 pathway, often due to KEAP1 mutations or epigenetic alterations, has been closely associated with resistance to cisplatin and increased metastasis." (PMID 40746900, 2025). "Numerous studies have shown that the Keap1 decrease in variety of cancers, including breast, ovarian, liver, non-small cell lung, colorectal, liver, gallbladder, head and neck squamous cell carcinoma." (PMID 37712005, 2023). "By focusing and genotyping head and neck squamous cell carcinoma (HNSCC) that had available pathologic and clinical data, we provide evidence that Keap1 displays frequent alterations (17%) in HNSCC." (PMID 35945195, 2022). "Alterations of the oxidative stress gene KEAP1 was reported in human papilloma virus negative head-and-neck squamous cell carcinomas (HNSCCs) (5%)." (PMID 26634163, 2015). "Here, we investigated the effects of pharmacological inhibition of Keap1 with ML344 on radiosensitivity, DNA double-strand break (DSB) repair and autophagy in head and neck squamous cell carcinoma (HNSCC) cell lines." (PMID 33087706, 2020). "Teng Xu and colleagues identified that, in head and neck squamous cell carcinoma (HNSCC), the DLG motif within tumor necrosis factor-α-induced protein 2 (TNFAIP2) competes with the Kelch domain of Keap1, thereby inhibiting the ubiquitin-proteasome-mediated degradation of NRF2." (PMID 40258841, 2025).
myocardial ischemia (13 papers, 2020 to 2025). A disorder of cardiac function caused by insufficient blood flow to the muscle tissue of the heart. "For instance, ursolic acid has been shown to bind to Kelch-like ECH-associated protein 1 (Keap1), facilitating its dissociation from Nrf2 and enabling Nrf2 to translocate into the nucleus, thereby reducing myocardial ischemia–reperfusion injury." (PMID 41301498, 2025). "In mice subjected to myocardial ischemia/reperfusion injury, suppression of Pgam5 interrupted Keap1-mediated Bcl-xL degradation and promoted cardiomyocyte survival." (PMID 37781037, 2023). "Urolithin B is a gut microbiota metabolite that protects against myocardial ischemia/reperfusion injury via the p62/Keap1/Nrf2 signaling pathway." (PMID 36216932, 2022). "Nrf2/Keap1 is an important signaling pathway for reducing myocardial infarct size and maintaining heart function following myocardial ischemia/reperfusion injury." (PMID 35710902, 2022). "Therefore, targeting the USP7-mediated Keap1 degradation pathway may be a new approach to prevent myocardial ischemia/reperfusion injury." (PMID 35710902, 2022). "In this study, abnormal elevation of Keap1 protein during myocardial ischemia/reperfusion was related to UPS disorder, which was confirmed by the return of Keap1 protein to normal level after treatment with USP7 inhibitor P5091." (PMID 35710902, 2022).